ALB (albumin)
Diseases named in the same sentence as ALB in open-access papers (continued):
Sharing a sentence is not in itself a finding about the gene and the disease.
metabolic disorders (62 papers, 2014 to 2026). "Serum ALB, as a marker of nutritional status, has attracted considerable attention due to its associations with OP related to inflammatory and metabolic disorders." (PMID 41041308, 2025). "Liver congestion reduces ALB synthesis, lipid transport, and synthesis, which can cause metabolic disorders." (PMID 38502317, 2024). "In the multivariable analyses, underlying metabolic disorders (adjusted hazard ratio [aHR], 2.85; 95% CI, 1.01–8.07) and serum albumin <3.5 g/dL (aHR, 2.26; 95% CI, 1.29–3.96) were risk factors for DILI during ATT." (PMID 37654787, 2023). "The metabolic disorder of uric acid and decreased albumin synthesis beforecardiac surgery may underlie the mechanism through which the UAR predicts AKI.Firstly, the kidney plays a significant role in uric acid excretion andabsorption." (PMID 40026514, 2025). "Conversely, nutrient deficiency and metabolic disorders will also aggravate the disease, affecting the prognosis of patients, forming a vicious cycle which may lead to lower albumin." (PMID 38923843, 2024). "Moreover, as indicated by the causal relationship between albumin and metabolic diseases revealed in this atlas, while lowering albumin levels may decrease CKD events, it might also increase the risk of metabolic diseases." (PMID 40973818, 2025). "Serum albumin levels were significantly reduced in the group with poor prognosis, which is a comprehensive reflection of metabolic disorder and gastrointestinal nutrition absorption disorder in the inflammatory state." (PMID 40800140, 2025). "Hepatic congestion reduces albumin synthesis and lipid transport andsynthesis, leading to metabolic disorders." (PMID 41209128, 2025). "In mammals, glycated serum albumin (gSA) contributes to the pathogenesis of many metabolic diseases by activating the receptors (RAGE) for advanced glycation end products (AGEs)." (PMID 38542178, 2024). "Low albumin levels reduce a patient's immunity, leading to drug absorption and metabolic disorders and complicating wound healing." (PMID 39193402, 2024). "The C-reactive protein-to-albumin ratio (CAR) is an inflammation-based marker with a prognostic value for several metabolic diseases." (PMID 38872964, 2024). "In adjusted analyses, having a metabolic disorder was identified as a risk factor for DILI (adjusted HR [aHR], 2.85; 95% CI, 1.01–8.07; P = .042), along with serum albumin <3.5 g/dL (aHR, 2.26; 95% CI, 1.29–3.96; P = .005)." (PMID 37654787, 2023). "Metabolic disorders (hazard ratio [HR], 3.17; 95% CI, 1.14–8.79; P = .027) and serum albumin level (<3.5 g/dL; HR, 2.36; 95% CI, 1.35–4.12; P = .003) were associated with DILI in univariable analyses." (PMID 37654787, 2023). "The metabolic disorders from this process cause NEFA and bilirubin elevated serum levels and decreased albumin concentrations." (PMID 37512868, 2023). "Accordingly, the physicochemical approach seems to be more accurate in the identification of metabolic disorders, since it takes into account both the levels of albumin and the alterations of electrolytes for the interpretation of the acid–base status." (PMID 38138927, 2023). "Metabolic disorders, old age (≥60 years), sex, and serum albumin level (<3.5 g/dL) were selected as variables using the forward conditional method in multivariable analyses." (PMID 37654787, 2023). "Palmitic acid (PA) is considered a major contributor to the inflammation in many metabolic diseases; however, this role has been questioned recently for the complicated procedures in preparing PA-bovine serum albumin (BSA) complex." (PMID 37079515, 2023). "In the bivariate analysis, several variables were found to be statistically significantly associated with DIC development, such as age ≥60 years, hematological cancer, metabolic disease, low albumin, and antibiotic treatment ≥1 h." (PMID 36362708, 2022).
metabolic disorders (continued). "Protein-energy wasting (PEW) is a common metabolic disorder in PD patients 4, and serum albumin (Alb) is an important index to evaluate PEW." (PMID 35983095, 2022). "Compared to UCB, CB may be more readily separated from albumin to protect patients from metabolism disorders." (PMID 38811905, 2024). "Measuring different blood forms of bilirubin, including unconjugated, free and albumin bound conjugated, DB and TB may provide critical information for the diagnosis of many diseases and metabolic disorders." (PMID 35886433, 2022). "Moreover, the direction of correlation between serum albumin and glycemic indices changed according to the observation points (baseline versus onset of metabolic disease)." (PMID 28430803, 2017). "Therefore, aggregation of bovine serum albumin is expected to adversely affect its transport ability including drug transport, thereby leading to several metabolic disorder." (PMID 28207877, 2017). "Similarly, elevated levels of total protein, albumin, urea, and uric acid may indicate metabolic diseases but may also be the body’s response to recent training." (PMID 40869529, 2025). "Whilst horse, rabbit and other farm animals are much lesser objects of research in the field of metabolic disorders, information on the mechanism of albumin interaction with the AGE/RAGE axis in these species could be useful, for example, for the selection of feed or in veterinary medicine." (PMID 38542178, 2024). "In addition, decreased albumin level also reflects worse liver function, which might imply more chances of metabolic disorder in liver cells." (PMID 38264288, 2023). "The preference of SARS-CoV-2 for AGE forms of glycated serum albumin may in part explain the severity and pathology of acute respiratory distress and the bias towards the elderly and those with (pre)diabetic and atherosclerotic/metabolic disease." (PMID 35456942, 2022). "Spleen deficiency might also lead to metabolic disorders such as lipid metabolism, amino acid metabolism, and energy metabolism, as evidenced by our results showed that NAFLD patients with SDS exhibited abnormalities in TP, ALB, LDL, and total cholesterol (TG) levels." (PMID 40861494, 2025). "Other significant findings included gastrointestinal, hepatic system, and metabolic disease, as well as lipid metabolism and increased levels of potassium, alkaline phosphatase (ALP), ALT, and albumin." (PMID 40034783, 2025). "Bovine serum albumin (BSA) is an important transport protein of the blood and its aggregation/fibrillation would adversely affect its transport ability leading to metabolic disorder." (PMID 28207877, 2017). "The uric acid to albumin ratio (UAR) is a novel marker which has been identified to possess a superior predictive ability for evaluating the severity of oxidative stress, inflammation, and metabolic disorders than using UA or ALB alone." (PMID 41602990, 2026). "Regarding nutritional status and metabolic disorders, we show that BMI does not change significantly after treatment in our cohort and does not correlate well with changes observed in cholesterol or albumin levels." (PMID 36831500, 2023). "In the nutrition indices of burn patients, both transferrin and albumin are acute phase proteins synthesized in the liver, and the metabolism of proteins can be sensitively reflected in patients without metabolic disorders." (PMID 27375697, 2016). "Additionally, as a complex metabolic disease, DKD involves not only inflammation but also classic pathological features of DKD, such as persistent albuminuria and Low-GFR, which often lead to decreased serum albumin levels." (PMID 40115740, 2025). "As the numbers of metabolic disorders increased, the SF levels, BMI, systolic BP (SBP), diastolic BP (DBP), fasting BG, TC, TG, serum uric acid (SUA), FINS, BFC, HOMA-IR, HOMA-β and urinary albumin/creatinine ratio (UACR) increased gradually; whereas the QUICKI and DI decreased gradually." (PMID 24926364, 2014).
metabolic disorders (continued). "Critical for metabolic applications, efgartigimod treatment did not reduce albumin levels despite the role of FcRn in albumin recycling and did not increase LDL cholesterol levels, supporting a therapeutic window for metabolic disease applications." (PMID 41425575, 2025).
immune dysfunction (44 papers, 2015 to 2025). "Low levels of albumin, total cholesterol, and lymphocytes count may cause immune dysfunction, leading to poor prognosis of MSA." (PMID 38075229, 2023). "Albumin infusions have also been shown to promote the reversal of immune dysfunction by binding and inactivating PGE2." (PMID 39273468, 2024). "ALB content is also an effective indicator of liver and immune dysfunction and was also significantly increased with dietary SBL supplementation, which is similar to the results in rainbow trout (Oncorhynchus mykiss)." (PMID 37110170, 2023). "Analysis of blood samples from patients with AD/ACLF participating in a feasibility study of 20% HAS infusions has shown that infusions to raise serum albumin above 30 g/L reversed plasma-mediated immune dysfunction by binding and inactivating PGE2." (PMID 28859868, 2018). "In an extended and larger sample size feasibility study of 20% HSA infusions, the same group has meanwhile confirmed that infusions to raise serum albumin above 30 g/L reversed plasma-mediated immune dysfunction." (PMID 30155448, 2018). "Strategies to improve humoral immunity and albumin status in patients with immune dysfunction should be further explored in an effort to reduce the incidence of CDI." (PMID 25899507, 2015). "Additionally, the co-variance in albumin levels and transaminase activity in IBD reflects underlying metabolic dysregulation and immune dysfunction." (PMID 41586218, 2025). "In addition, albumin is the main protein synthesized in the liver and can be negatively affected by inflammation, reflecting systemic inflammatory and immune dysfunction." (PMID 37340352, 2023). "Albumin is a surrogate marker for a heightened inflammatory state; thus, a low albumin may correlate to a more advanced disease state or immune dysfunction." (PMID 36290885, 2022). "As for HIV-related HCC, the largest single-arm multicenter study of 387 HIV-infected patients with HCC showed that the albumin-bilirubin grade highlights the interplay between liver reserve and immune dysfunction as a potential prognostic factor for the survival of patients with HIV+ HCC." (PMID 35321670, 2022). "Again we observed heterogeneity in immune dysfunction and response to albumin using our immune assay may identify patients most likely to benefit from this approach." (PMID 28859868, 2018). "ALB/GLB ratio may become a new research direction for immune diseases in the future." (PMID 37752439, 2023). "Targeted albumin infusions effectively increased serum albumin levels to 30 g/L or greater in hospitalized AD/ACLF patients; a level below which we previously identified as predicting immune dysfunction." (PMID 28911947, 2018). "Albumin, which reduces PGE2 bioavailability, was decreased in the serum of patients with acute decompensation and appears to have a role in modulating PGE2-mediated immune dysfunction." (PMID 39273468, 2024). "We also found that ALB/GLB in AS and other immune diseases may become a new research hotspot in the future." (PMID 37752439, 2023). "Additionally, immune dysfunction (CD4+ < 500 cells/μl) exhibited negative correlations with BMI, PNI, TP, ALB, PA, and TRF." (PMID 39086487, 2024).
respiratory disease (41 papers, 2011 to 2026). "The study observed a gradual increase in albumin levels from group Q1 to Q4, accompanied by a progressive decrease in mortality from all causes, as well as cardiovascular and respiratory diseases." (PMID 40443682, 2025). "Previous studies report that low albumin levels are associated with increased mortality in various respiratory diseases, possibly reflecting poor nutritional status." (PMID 37831431, 2023). "Low albumin is reportedly associated with increased incidence of all-cause mortality, cancer-related mortality, cardiovascular disease, respiratory disease, and other adverse outcomes." (PMID 37947552, 2023). "APACHE II score (0 points for 0–14, 1 point for 15–19, and 2 points for ≥30), qSOFA score ≥ 2 (2 points), serum albumin level < 3.4 g/dL (1 point), and infectious or respiratory disease (1 point) were incorporated into risk scoring system for mortality." (PMID 34356231, 2021). "Marginal associations were observed for respiratory disease, low serum albumin levels at ICU admission, and use of antifungal antibiotics during the ICU stay." (PMID 33573691, 2021). "Our results showed a similar pattern, namely, an association between presence of respiratory disease and low albumin level." (PMID 27276092, 2016). "Additionally, the mortality risk from respiratory disease was double in patients with albumin levels <4.0 g/dL." (PMID 37947552, 2023). "This was thought to be secondary to noncardiovascular factors, including a poorer nutritional baseline, as evidenced by low albumin being most significant, and respiratory disease." (PMID 40908085, 2025). "We then evaluated the shared genetics of hsCRP and albumin with it significantly related lung function parameters and respiratory diseases." (PMID 38704398, 2024). "In contrast, much less identified shared loci of GlycA with lung function parameters and respiratory diseases were identified to be share between albumin and lung function or respiratory diseases." (PMID 38704398, 2024). "The proportion of some comorbidities were even higher in 2012 than in 2006: 17.6% of patients had a respiratory disease in 2012 vs. 14.1% in 2006 (p = 0.001), and 25.5% had serum albumin concentration &lt; 30 g/l in 2012 vs. 19.6% in 2006, p = 0.004." (PMID 30223784, 2018). "The relation of respiratory disease to serum albumin and economic status and the pathway from low income to respiratory disease need to be acknowledged and addressed." (PMID 27276092, 2016). "Blood samples were taken from calves with respiratory disease the first day of examination for determination of the serum concentration of haptoglobin, fibrinogen, α-2- and γ-globulins, and albumin." (PMID 21430962, 2011). "Serum albumin is extensively involved in the development of various respiratory diseases." (PMID 39026682, 2024). "Multisite colonization, polymicrobial colonization, catheterization and receiving albumin after colonization, concomitant respiratory diseases, receiving carbapenems and antimicrobial combination therapy before CRE colonization within 90 days were included in final model." (PMID 38659068, 2024). "Similarly, in addition to serum albumin level, presence of respiratory disease was statistically significant in the model predicting dyspnea (OR = 2.79, 95% CI 1.54–5.08, P = 0.0008)." (PMID 35189828, 2022). "All these studies suggest that serum albumin level may be used as a prognostic indicator of mortality in premature infants, especially respiratory diseases." (PMID 34485188, 2021). "Therefore, we considered that our study might suggest a supplement to the BUN/ALB ratio as a prognostic factor for respiratory diseases." (PMID 36522751, 2022). "Serum albumin was linearly and positively correlated with FEV 1 in those with previous respiratory disease (β = 228.90, 95% CI = 73.89–383.91, p = 0.0040)." (PMID 36262258, 2022).
respiratory disease (continued). "On multivariable analysis, functional decline was associated with comorbidities (global CIRS-G score, P = 0.02, CIRS-G for respiratory disease [CIRS-G-R] ≥2, P = 0.02, or psychiatric disease, P = 0.02) and albumin level < 35 g/l (p = 0.03)." (PMID 33121435, 2020). "In those without respiratory disease, serum albumin was linearly negatively correlated only with FEV 1 (β = -0.79, 95% CI = -1.57 to -0.01, P = 0.0471)." (PMID 36730242, 2023). "Serum albumin was also linearly and positively correlated with FEV 1 in those who had not had respiratory disease (β = 163.86, 95% CI = 98.00–229.73, p < 0.0001), and the correlation was similar in both groups (P-interaction = 0.256)." (PMID 36262258, 2022).
kidney (39 papers, 2007 to 2026). "In the presence of kidney injury or disease, particularly when the glomerular filtration membrane is compromised, a significant loss of proteins occurs, leading to a reduction in serum albumin levels." (PMID 40800596, 2025). "An increase in SBP, logUACR or uric acid, and a decrease in HDL, FFA, hematocrit, hemoglobin or albumin were significantly associated with an increased risk of the composite kidney outcome when analyzed as time-dependent updated mean or landmark Week 12 current change." (PMID 38323492, 2024). "In this exploratory study, we will assess whether there are blood-based gene expression biomarkers that correlate with phenotypically determined kidney risk groups based on a composite of two key markers of CKD (urine albumin excretion and eGFR)." (PMID 33822824, 2021). "In line with our results, earlier studies already described endothelial edema preceding FITC-albumin early after middle cerebral artery occlusion, another model system for studying BBB leakiness." (PMID 39102289, 2024). "The kidneys of the diabetic mice presented with the expected increased kidney weight/body weight ratio and urinary albumin, indicative of kidney dysfunction." (PMID 31699972, 2019). "Consistent with our cohort, proteinuria >0.05 g/mmol (equivalent to protein-to-creatinine ratio 500 mg/g and albumin-to-creatinine ratio 300 mg/g) was identified as a risk factor for adverse kidney outcomes, including a higher risk of ESKD, death, and kidney relapse." (PMID 40008353, 2025). "The urine albumin-to-creatinine ratio (ACR) is a kidney damage marker." (PMID 35408760, 2022). "By monitoring serum EN-RAGE, sRAGE, EN-RAGE/sRAGE value and clinical parameters for these patients, we found that posttreatment group showed a striking reduction of ALT and AST but improved level of ALB, implying that there is a mitigation of liver damage and recovery of liver functions." (PMID 33036620, 2020). "Male LinSTZ mice had elevated water intake, urine output, urinary albumin to creatinine ratio (ACR), kidney lesion score, and creatinine clearance compared to the Lin control group." (PMID 38055691, 2023). "Indicators of kidney injury and CKD was determined by the estimated glomerular filtration rate and the urinary albumin to creatinine ratio." (PMID 37081921, 2023). "A negative correlation was observed with a history of a previous kidney transplant, LVEF, diastolic blood pressure (BP), mean BP, serum albumin and creatinine." (PMID 28882110, 2017). "Alone administration of CPZ induced a significant increase in serum level of ALT, AST, ALB, TBIL in rats as compared to normal control group, suggested that CPZ exposure has successfully lead to cholestatic liver injury." (PMID 25887351, 2015). "Furthermore, in mouse chronic liver injury studies, MCAM is enriched in hepatocyte derived proliferative ducts, over those derived from mature BECs alongside AHSG, ALB, CAV1 and RBP48." (PMID 31350390, 2019).